MRPL39 (mitochondrial ribosomal protein L39)
Synonyms: L39mt; L5mt; MRP-L5; C21orf92; MRPL5; RPML5; MSTP003; PRED22; MGC104174; PRED66; MGC3400; FLJ20451; mL39; COXPD59
Tractability: Small molecule: a structure with a bound ligand is known. PROTAC: ubiquitination databases record sites on it; its protein half-life has been measured.
Gene: Protein-coding gene on chromosome 21 (25,585,632 to 25,607,525, reverse strand). Ensembl gene ENSG00000154719.
Subcellular location: Mitochondrion
Subcellular location (Human Protein Atlas): Mitochondria
Pathways (Reactome):
Metabolism of proteins: Mitochondrial ribosome-associated quality control; Mitochondrial translation elongation; Mitochondrial translation initiation; Mitochondrial translation termination
Gene Ontology:
Molecular function: RNA binding; nucleotide binding
Biological process: mitochondrial translation
Cellular component: mitochondrial large ribosomal subunit; mitochondrion; mitochondrial inner membrane; mitochondrial ribosome
Genetic constraint (gnomAD): Loss-of-function variants: 33 observed, 37.47 expected, observed/expected ratio (o/e) 0.88, 90% interval 0.67 to 1.18. The upper end of that interval is the gene's LOEUF score, 1.18, which puts it in group 5 of 6, group 1 being the genes least tolerant of losing a copy. Missense variants: 375 observed, 356.4 expected, observed/expected ratio (o/e) 1.05, 90% interval 0.97 to 1.15. Synonymous variants: 123 observed, 120.78 expected, observed/expected ratio (o/e) 1.02, 90% interval 0.88 to 1.18.
Gene-disease validity (ClinGen):
ClinGen rates the evidence that MRPL39 causes each of these diseases.
mitochondrial disease (autosomal recessive): Moderate.
Homologues: Orthologues: chimpanzee MRPL39 (94% identical), macaque MRPL39 (93% identical), pig MRPL39 (89% identical), guinea pig MRPL39 (88% identical), rabbit MRPL39 (88% identical), dog MRPL39 (87% identical), mouse Mrpl39 (84% identical), rat Mrpl39 (82% identical), tropical clawed frog mrpl39 (60% identical), zebrafish mrpl39 (45% identical), Drosophila melanogaster mRpL39 (36% identical), Caenorhabditis elegans mrpl-39 (18% identical). Paralogues in human: TARS3 (24% identical), TARS1 (24% identical), TARS2 (21% identical), PARS2 (12% identical).
Diseases named in the same sentence as MRPL39 in open-access papers:
MRPL39 is named in the same sentence as 16 diseases in open-access papers, as found by Europe PMC text mining. Sharing a sentence is not in itself a finding about the gene and the disease. The quoted sentences say what the papers report.
gastric cancer (4 papers, 2019 to 2025). A primary or metastatic malignant neoplasm involving the stomach. "Conversely, the expression of MRPL39 is significantly downregulated in gastric cancer tissues and cell lines, and low expression is closely associated with clinical features of the tumor, especially tumor size and TNM staging." (PMID 40371222, 2025). "Gastric cancer patients with low levels of MRPL39 expression have significantly shorter OS and DFS." (PMID 40371222, 2025). "And MRPL39 hindered the progression of gastric cancer via the direct interaction with miR-130." (PMID 32280304, 2020). "Another study has represented that MRPL39 serves as a tumor suppressor by directly targeting miR-130 in gastric cancer, suggesting that it may be a new gastric cancer biomarker for diagnosis and prognosis." (PMID 33238645, 2020). "Inactivation of tumor suppressor genes such as RPS7, MRPL39, MRPS23, ME2, and NDUFB9 were diagnosed with the development of many cancer types such as colorectal cancer, gastric cancer, breast cancer, and pancreatic cancer, but loss of these genes may be responsible for the development of GBM." (PMID 31137733, 2019). "This suggests that the roles of MRPL39,MRPS5,and DAP3 in gastric cancer may be complex." (PMID 40371222, 2025).
ovarian carcinoma (3 papers, 2021 to 2025). A malignant neoplasm originating from the surface ovarian epithelium. "Kaplan-Meier survival analysis shows that high expression of MRPL15, MRPL36, MRPL39, and MRPS16 is significantly associated with poorer OS in ovarian cancer patients." (PMID 40371222, 2025). "In ovarian cancer, MRPL39 was among the top six MRPs whose expression correlated with tumorigenicity, including advanced stage and poor survival." (PMID 39354291, 2024). "MRPL10, MRPL15, MRPL36, MRPL39, and MRPS16 were highly expressed in ovarian cancer, whereas MRPS31 showed the opposite tendency." (PMID 33934540, 2021). "The expression of all six MRPs in ovarian cancer was positively correlated, with the strongest correlation being between MRPS16 and MRPL39 (r = 0.56, p < 2.2e‐16)." (PMID 33934540, 2021). "Six MRPs (MRPL10, MRPL15, MRPL36, MRPL39, MRPS16, and MRPS31) related to HE4 in ovarian cancer were selected." (PMID 33934540, 2021).
colorectal cancer (2 papers, 2019 to 2024). A primary or metastatic malignant neoplasm that affects the colon or rectum. "Notably, in a colorectal cancer study, MRPL39 was associated with reduced metastasis." (PMID 39354291, 2024). "Studies in ovarian, lung, and colorectal cancers, provide some insight into the potential mechanisms of MRPL39 in tumour progression and metastasis." (PMID 39354291, 2024).
diabetic retinopathy (1 paper, 2022). "Currently, many studies have demonstrated that MRPL39 plays a part in a variety of cancers, but the investigation of MRPL39 in diabetic retinopathy remains insufficient." (PMID 36186470, 2022).
nasopharyngitis (1 paper, 2023). An inflammatory process that affects the nasopharynx. "Lnc-MRPL39-2:1 expression was negligible in nasopharyngitis tissues, whereas upregulated lnc-MRPL39-2:1 expression was detected in 75.4% of the NPC samples (92/122) had a higher lnc-MRPL39-2:1 expression." (PMID 37215987, 2023).
retinitis pigmentosa (1 paper, 2018). Retinitis pigmentosa (RP) is an inherited retinal dystrophy leading to progressive loss of the photoreceptors and retinal pigment epithelium and resulting in blindness usually after several decades. "At least three other MRP genes; MRPL9, MRPL23, and MRPL39 map to genomic regions associated with retinitis pigmentosa indicating the importance of this pathway in retinal pathology." (PMID 29739359, 2018).
cancer (8 papers, 2019 to 2023). A tumor composed of atypical neoplastic, often pleomorphic cells that invade other tissues. "Dysregulation or mutations in MRPL39 can lead to mitochondrial dysfunction, associated with various human diseases such as metabolic disorders, neurodegenerative diseases, and cancer." (PMID 37754259, 2023). "As miR-25-5p may be sponged via phenanthriplatin-mediated upregulation of lnc-MRPL39-10, this miRNA could be downregulated in A549 cells, which is associated with anti-cancer effect via PI3K signaling." (PMID 34001990, 2021). "Approximately 130 proteins were detected by MS analysis of the corresponding band, including the RNA binding protein (RBP) HuR, which is involved in the post-transcriptional regulation of cancer-related gene expression and interacts directly with lnc-MRPL39-2:1." (PMID 37215987, 2023). "Although, our findings provide insights into the value of lnc-MRPL39-2:1 as a promising therapeutic target against NPC, further studies are required to develop precise strategies targeting lnc-MRPL39-2:1 signaling and clarify the role of lnc-MRPL39-2:1 in other cancers." (PMID 37215987, 2023).
tumor (6 papers, 2021 to 2025). "Higher levels of MRPL39 were observed in cells with lower metastatic potential, suggesting a tumour suppressive role." (PMID 39354291, 2024). "We observed a remarkable elevation in the final tumor weight and volume of tumors in the lnc-MRPL39-2:1 overexpression group compared to the control group, indicating that lnc-MRPL39-2:1 significantly promoted tumor growth." (PMID 37215987, 2023). "Using lncRNA arrays to analyze the lncRNA profiles of the NPC and para-tumor tissues, we detected the novel lnc-MRPL39-2:1, which was validated by in situ hybridization and by the 5' and 3' rapid amplification of the cDNA ends." (PMID 37215987, 2023). "The results indicated that lnc-MRPL39-2:1 was expressed at a high level in NPC tumors compared to non-tumor tissues." (PMID 37215987, 2023). "We identified a novel oncogenic lncRNA, lnc-MRPL39-2:1 that was upregulated in NPC tissues and associated with advanced tumor stage and poor prognosis of patients." (PMID 37215987, 2023). "Notably, one lncRNA was also identified in our “top” hit list, MRPL39, which acts as a tumour suppressor in gastric cancer." (PMID 38653965, 2024). "Therefore, in this study, we have investigated the lncRNA profiles of the NPC and para-tumor tissues and detected the novel lncRNA sequence, i.e., lnc-MRPL39-2:1." (PMID 37215987, 2023). "Another protein MRPL39 was reported to serve as a tumor suppressor." (PMID 34899304, 2021). "The expression levels of the lnc-MRPL39-2:1 were dependent on many factors, including the NPC patients' tumor (T) stage, nodes (N) stage, and the tumor-node-metastasis (TNM) stage." (PMID 37215987, 2023). "Having observed the pivotal role of lnc-MRPL39-2:1 in promoting NPC growth and invasion in vitro, we then confirmed its role in NPC progression in vivo in a nide mouse tumor xenograft model." (PMID 37215987, 2023). "Tumor cells invasion was observed in the epidermal appendages in the lnc-MRPL39-2:1 group but not in the control group." (PMID 37215987, 2023). "Finally, to determine the role of HuR in the tumor-promoting effects of lnc-MRPL39-2:1, CNE2 and HONE1 cells were transfected with lnc-MRPL39-2:1-overexpression vector and si-HuR." (PMID 37215987, 2023). "Using quantitative PCR (qPCR) and the RNA-fluorescence In Situ Hybridization (RNA-FISH) techniques for validation, we confirmed lnc-MRPL39-2:1 was significantly upregulated in NPC tumor tissues compared with non-tumor tissues." (PMID 37215987, 2023). "Similarly, in the current study, we found that lnc-MRPL39-2:1, which was upregulated in NPC tissues, was positively correlated with late tumor stage and poor survival of patients, thus indicating that lnc-MRPL39-2:1 may be a vital prognostic factor in NPC." (PMID 37215987, 2023).
mitochondrial disease (3 papers, 2023 to 2025). "The mitochondrial ribosomal protein MRPL39 is involved in pediatric onset of mitochondrial disease and is upregulated in L3 DS PNs." (PMID 39605035, 2024). "One disease-affected control cell line derived from a patient with likely pathogenic variants in MRPL39 (ClinVar Accession IDs VCV001676672.1 and VCV001676674.2) and presenting with severe paediatric mitochondrial disease were also used for comparison." (PMID 37148394, 2023).
infection (1 paper, 2016). The state of being infected such as from the introduction of a foreign agent such as serum, vaccine, antigenic substance or organism. "At 8wks post infection, the most prominent genes which were significantly up-regulated in the liver tissue encode MCM, NDUF1, AACS, P450RAI-2, DARS, MRPL39, SOD1, associated with mitochondrial respiration and aerobic metabolism." (PMID 27467147, 2016).
MRPL39 also shares sentences with these, for which no sentence is quoted: Down syndrome (2 papers); breast carcinoma (1); metabolic disorders (1); nasopharyngeal carcinoma (1); neurodegenerative disease (1); pancreatic cancer (1).